SPOP (speckle type BTB/POZ protein)
Diseases named in the same sentence as SPOP in open-access papers (continued):
Sharing a sentence is not in itself a finding about the gene and the disease.
gastric cancer (14 papers, 2014 to 2025). A primary or metastatic malignant neoplasm involving the stomach. "Speckle-type POZ (SPOP) is a unique protein in that it at times inhibits Hh signaling in gastric cancer through increasing the degradation of Gli2, while SPOP can also upregulate Hh signaling, decreasing CRC CSC’s rate of apoptosis." (PMID 37305676, 2023). "It is well-known that dramatically decreased SPOP expression is negatively correlated with tumorigenesis in gastric cancer tissues." (PMID 36474188, 2022). "Limited studies suggest that SPOP suppresses tumour development by negatively regulating the Hedgehog/Gli2 signalling pathway in gastric cancer." (PMID 36474188, 2022). "For example, SPOP has a definitive tumour suppressing role in gastric cancer by promoting the degradation of the transcription factor Gli2 of the Hedgehog (Hh)/Gli2 signalling pathway." (PMID 36474188, 2022). "SPOP transfection of gastric cancer cell lines inhibited cell proliferation, migration, and colony formation." (PMID 34572373, 2021). "Firstly, a previous study demonstrated that the expression of SPOP was higher in adjacent or normal gastric tissues than that in gastric cancer." (PMID 34838022, 2021). "Of these, miR‐543 has been reported to promote cell migration and invasion by targeting SPOP in gastric cancer." (PMID 33047885, 2020). "Intracellular interaction of SPOP and Gli2 was visualized by immunofluorescent staining in gastric cancer cells." (PMID 25204354, 2014). "In vitro experiments revealed that over-expression of SPOP prevented tumor cells from proliferation, migration and colony formation in gastric cancer cell lines." (PMID 25204354, 2014). "In this study, we characterized the expression of SPOP in 88 pairs of gastric cancer tissues and adjacent tissues by immunohistochemical staining and Western blotting." (PMID 25204354, 2014). "Taken together, these results indicate that SPOP plays critical roles in gastric cancer cell apoptosis." (PMID 25204354, 2014). "Our results indicate that SPOP reduces gastric cancer cell invasion and proliferation by regulating Hh/Gli2 signaling pathway." (PMID 25204354, 2014). "Immunohistochemical staining of SPOP can be detected in gastric cancer tissues but much less than adjacent gastric tissues (P < 0.01)." (PMID 25204354, 2014). "Dramatically decreased SPOP expression in GC tissues indicates a role of it in gastric cancer processing." (PMID 25204354, 2014). "In vitro experiments provide evidence that SPOP functions as a tumor suppressor in different gastric cancer cell lines and contributes to post-transcriptional modification of Gli2." (PMID 25204354, 2014). "Therefore, we utilize plasmid transfected gastric cancer cells to observe effects of over-expressed or repressed SPOP on apoptosis." (PMID 25204354, 2014). "Since the active form of Caspase-3 (cleaved Caspase-3) marks the frequency of cell apoptosis, we examined the expression of cleaved Caspase-3 in SPOP over-expressed gastric cancer cells and gastric cancer tissues by immunofluorescent and immunohistochemical staining methods." (PMID 25204354, 2014). "The identification of SPOP as a negative regulator of Gli2-mediated transcription may provide an alternative strategy for developing therapeutic agents for gastric cancer in future." (PMID 25204354, 2014). "In this study, we evaluated SPOP expression in gastric cancer tissues and adjacent gastric tissues." (PMID 25204354, 2014). "However, apoptotic function of SPOP in gastric cancer was seldom studied." (PMID 25204354, 2014). "Likewise, SPOP repression enhanced GLI1/2 levels, which consequently promoted gastric cancer cell proliferation and migration as well as attenuated apoptosis." (PMID 34572373, 2021). "Conversely, significant results also revealed that low expression of SPOP was positively associated with LNM in non-ccRCC, such as CRC, gastric cancer, and NSCLC." (PMID 31577764, 2019).
gastric cancer (continued). "However, in our gastric cancer cell line MKN45, different from ccRCC study, tumor suppressor PTEN was reduced and p-ERK was activated when SPOP was repressed." (PMID 25204354, 2014). "In high power field, SPOP was mainly expressed in the cytoplasm and nuclear of adjacent gastric mucosa epithelium cells but less or no staining in gastric cancer cells." (PMID 25204354, 2014).
clear cell renal cell carcinoma (13 papers, 2014 to 2025). "SPOP encodes an E3 ubiquitin ligase component, and in clear cell renal cell carcinoma, it is a transcriptional target of HIFs." (PMID 37382594, 2023). "Although previous studies have shown that SPOP promotes tumor progression by activating the β-catenin/TCF4 complex in clear cell renal cell carcinoma, we found that SPOP inhibits CRC progression by degrading β-catenin." (PMID 41213915, 2025). "Previous studies have validated SPOP as an attractive target for the treatment of clear-cell renal cell carcinoma (ccRCC) and reported the first SPOP inhibitor, but it is a challenging target in terms of protein–protein interactions." (PMID 37452028, 2023). "In clear cell renal cell carcinoma, SPOP drives EMT and promotes cell invasion via activation of β-catenin/TCF4 complex." (PMID 37382594, 2023). "Counterintuitively, SPOP is overexpressed in other cancer types such as clear cell renal cell carcinoma, where it acts as a tumorigenic hub, indicating that the role of SPOP in cancer is likely tumor type dependent." (PMID 32512734, 2020). "One study demonstrated that hypoxia condition promotes SPOP cytoplasmic accumulation in clear cell renal cell carcinoma (ccRCC) cells." (PMID 28448495, 2017). "Although E3 ligase Speckle type BTB/POZ protein (SPOP) promotes tumorigenesis by acting as a key regulatory hub in clear cell renal cell carcinoma (ccRCC), the detailed molecular mechanism remains unclear." (PMID 34021128, 2021). "A recent published study of clear cell renal cell cancer (ccRCC) raises another question that SPOP acts as multiple regulators of cellular proliferation and apoptosis, including not only Gli2 but also tumor suppressor - PTEN, ERK phosphatases and pro-apoptotic molecule Daxx." (PMID 25204354, 2014). "Thus the total effect of SPOP on clear cell renal cell carcinoma is promoting tumorigenesis." (PMID 25204354, 2014). "In line with our finding that SPOP could be critical for lowering the tumor-suppressive levels of IRF1, SPOP is overexpressed in most clear-cell renal cell carcinomas (ccRCC)." (PMID 37622993, 2023). "Interestingly, one study recently demonstrates that SPOP knockdown leads to PTEN accumulation and AKT inactivation in the clear cell renal carcinoma (ccRCC) cells." (PMID 34353330, 2021). "Previous work showed that SPOP is overexpressed in virtually all clear cell renal cell carcinomas (ccRCCs), which accounts for about 75% of all RCC cases, and that overexpressed SPOP, which is a nucleoprotein in normal cells, accumulates in the cytoplasm of ccRCC cells." (PMID 34691990, 2019).
lung carcinoma (13 papers, 2017 to 2025). "These associations include APC/CDC20 for EML4-ALK fusions in lung cancers, SPOP for NUP98-NSD1 and BCR-ABL fusions in LAML, and FBW7 (or FBXW7, F-box and WD repeat domain containing 7) for CCDC6-RET fusions in thyroid carcinomas (THCAs)." (PMID 34795215, 2021). "Taken together, we speculated that SPOP gene hypermethylation could be associated with lung cancer pathogenesis." (PMID 30607139, 2018). "A series of experiments are conducted to demonstrate that maprotiline targets SPOP, resulting in the degradation of PD‐L1 and the activation of T cells, thereby suppressing the progression of colon and lung cancers." (PMID 39499771, 2025). "In conclusion, our results indicate that SPOP is essential for the C/EBPα-regulated suppression of migration and invasion in lung cancer cells." (PMID 30607139, 2018). "The C/EBPα expression plasmid or C/EBPα siRNA was transiently transfected into A427 or H1299 cells, respectively, to investigate the role of C/EBPα in SPOP expression regulation in lung cancer cells." (PMID 30607139, 2018). "The results indicated that the SPOP promoter region was highly methylated in the lung cancer cell lines A549, A427 and H1229 but lowly methylated in the normal bronchial cell line 16HBE." (PMID 30607139, 2018). "Although several studies investigating the relationship between SPOP and cancer have been performed, knowledge regarding the role of SPOP in lung cancer is limited." (PMID 30607139, 2018). "Additionally, we analyzed the expression levels of PD‐L1 and SPOP in both paracancerous and cancerous tissues of patients with colon and lung cancer." (PMID 39499771, 2025). "Targeting the SPOP-FADD axis presents a promising therapeutic strategy in lung cancer." (PMID 40521202, 2025). "Previous studies have reported that SPOP plays a role in cell growth suppression in NSCLC cells; therefore, we speculated that SPOP mediates the C/EBPα-suppressed proliferation in lung cancer cells." (PMID 30607139, 2018). "Furthermore, studies have shown that SERPINA3 plays a role in inhibiting lung cancer progression through the SPOP/NF-κB signaling axis, suggesting that targeting SPOP could provide a promising therapeutic approach to enhance radiation therapy outcomes in LUAD." (PMID 40710178, 2025). "In lung cancer and DLBCL, SPOP regulates cell proliferation, migration, invasion, and NF-κB signaling 87-90." (PMID 40521202, 2025). "In non–small cell lung cancer (NSCLC), SPOP expression is downregulated and significantly correlated with unfavorable clinical outcomes, suggesting its potential role as a tumor suppressor gene in NSCLC." (PMID 41122967, 2025). "Similarly, in other cancers, including lung cancer, diffuse large B-cell lymphoma (DLBCL), choriocarcinoma, and Ewing sarcoma, SPOP also exerts tumor-suppressive functions." (PMID 40521202, 2025). "Our study found that the CpG sites in the SPOP promoter region were hypermethylated in NSCLC tissues and A549, A427 and H1299 lung cancer cells but hypomethylated in adjacent non-tumor tissues and 16HBE cells." (PMID 30607139, 2018).
prostate adenocarcinoma (12 papers, 2017 to 2025). "SPOP, a frequently mutated E3 ubiquitin ligase in PCa, can bind to and ubiquitinate AR in prostate adenocarcinoma cells, while prostate adenocarcinoma-associated SPOP mutations abolish this activity." (PMID 38275816, 2024). "Our analysis shows frequent mutations and amplifications of SPOP in TCGA PRAD (prostate adenocarcinoma) and UCEC (uterine corpus endometrial carcinoma) cohorts." (PMID 35975235, 2022). "It is noteworthy that SPOP mutations are found at higher frequency in prostate adenocarcinomas (Pca) than CRPCs or NEPCs48." (PMID 34795264, 2021). "This included SPOP, which was exclusively mutated in prostate adenocarcinoma, and RXRA, where 80% of mutations were observed in the bladder urothelial cancer." (PMID 29572294, 2018). "Additionally, SPOP is frequently dysregulated through somatic mutations or mRNA down-regulation, indicating its crucial role as a tumor suppressor in prostate adenocarcinoma." (PMID 40034124, 2025). "The co-occurrence between SPOP mutations and RGMB-AS1 deletion happened exclusively in prostate adenocarcinoma (PRAD)." (PMID 33333852, 2020). "Additionally, it has identified c-MYC as a novel and authentic substrate of SPOP and provided insights into the frequent inactivation of SPOP in human prostate adenocarcinoma." (PMID 40034124, 2025). "Using the ‘The Cancer Genome Atlas’ Prostate Adenocarcinoma (TCGA PRAD) database, significant correlations were found between high CPSF4 expression and high-risk genomic abnormalities such as ERG-fusion, ETV1-fusion, and SPOP mutations." (PMID 37629142, 2023). "In particular, we found none of the ERG-family fusion genes or structural variants, no SPOP mutations, no further FOXA1 mutations, and none of the recurrent whole chromosomal aneuploidies seen in prostate adenocarcinoma." (PMID 33657416, 2021).
liver cancer (11 papers, 2020 to 2025). An epithelial or non-epithelial malignant neoplasm that arises from the liver. "Furthermore, we identify a liver cancer-associated SPOP mutation, M35L, in its MATH domain." (PMID 38409107, 2024). "For instance, in HCC, OGT highly O-GlcNAcylates speckle-type POZ protein (SPOP) at Ser96, facilitating its nuclear entry and inhibiting apoptosis of liver cancer cells." (PMID 39285476, 2024). "Studies have identified the critical role of SPOP in regulating proliferation and migration in liver cancer." (PMID 36575369, 2022). "Previous studies have demonstrated that SPOP can suppress or promote tumorigenesis in a variety of malignancies, including lung, colon, gastric, prostate, and liver cancers." (PMID 36042498, 2022). "Numerous studies have determined that SPOP suppresses tumorigenesis in a variety of human malignancies such as prostate, lung, colon, gastric, and liver cancers." (PMID 31901237, 2020). "Similarly, SPOP expression was found to be abnormally low in liver cancer cell lines compared to normal liver cells." (PMID 40483310, 2025). "Given that IRF2BP2 exhibits potent tumor-suppressor activity in the hepatocellular carcinoma (HCC), we explored whether IRF2BP2 is an authentic SPOP substrate primarily in liver cancer cells." (PMID 38409107, 2024). "SPOP, as an important protein molecule involved in the regulation of the occurrence and development of various tumors, has limited reports regarding its molecular mechanism in liver cancer metastasis." (PMID 37941785, 2023). "In addition, SPOP expression in adjacent tissue was significantly higher than that in cancer tissue in prostate and liver cancer." (PMID 34838022, 2021). "In addition, SPOP expression of adjacent tissue was significantly higher than that in cancer tissue in prostate and liver cancer." (PMID 34838022, 2021). "Meanwhile, it was also reported that SPOP played a favorable prognostic factor for liver cancer and might act as a novel tumor suppressor for tumor progression." (PMID 34838022, 2021). "Moreover, SPOP expression is significantly downregulated in liver cancer and colorectal cancer." (PMID 40483310, 2025). "The SPOP expression of adjacent tissue was significantly higher than that in cancer tissue of prostate (RR 1.73, 95% CI 1.19–2.51, I2 = 74%, random effect model, 3 comparisons, 230 cases) and liver cancer (RR 1.48, 95% CI 1.25–1.76, I2 = 45%, fix effect model, 2 comparisons, 184 cases)." (PMID 34838022, 2021). "Importantly, IHC staining analysis revealed a negative correlation between SPOP and LMNB2 expression in liver cancer tissues." (PMID 40483310, 2025).
hepatocellular carcinoma (9 papers, 2021 to 2025). A malignant tumor that arises from hepatocytes. "Specifically, in HCC, SPOP is highly O-GlcNAcylated by O-GlcNAc transferase (OGT) at Ser96, which enhances the nuclear localization of SPOP in hepatoma cells." (PMID 40521202, 2025). "O-GlcNAcylation at Ser96 was shown to alter SPOP localization, moving it predominantly into the nucleus in hepatoma cells." (PMID 39199296, 2024). "For instance, Huang’s team reported that SPOP could inhibit hepatoma cell migration, including the suppression of ZEB2 expression and the related program of epithelial–mesenchymal transition." (PMID 37941785, 2023). "At present, the role of SPOP in hepatocellular carcinoma (HCC) has rarely been studied." (PMID 37941785, 2023). "It has been shown that MDM2 oncoprotein ovexpression is frequently observed in hepatocellular carcinoma (HCC), Thus, MDM2's negative regulation on SPOP adds another layer of impact of MDM2 overexpression in HCC." (PMID 38308184, 2024).
cervical carcinoma (7 papers, 2019 to 2025). A carcinoma arising from either the exocervical squamous epithelium or the endocervical glandular epithelium. "Here, we report that DRAK1 protein was specifically degraded through K48-linked polyubiquitination induced by CUL3/SPOP E3 ubiquitin ligase in paclitaxel-resistant cervical cancer cells." (PMID 35194034, 2022). "In cervical cancer, SPOP seems to promote paclitaxel resistance and diminish the efficacy of immune therapies, thereby contributing to tumor progression 72,77; however, these findings warrant further investigation." (PMID 40521202, 2025). "We have previously demonstrated that SPOP gene can promote the metastasis of cervical cancer by regulating the spatial distance between PD-1 and PD-L1 genes." (PMID 37254049, 2023). "SPOP promotes cervical cancer progression by inducing the movement of PD-1 away from PD-L1 in spatial localization." (PMID 37768206, 2023). "Metastasis is a major obstacle in the treatment of cervical cancer (CC), and SPOP-mediated regulatory effects are involved in metastasis." (PMID 36042498, 2022). "The same interaction was observed for human and mouse MyD88 and SPOP in human cervical carcinoma cells (Hela cells) and Chinese hamster ovary cells (CHO cells)." (PMID 32365080, 2020).
colon cancer (7 papers, 2017 to 2025). "Speckle-type POZ protein (SPOP) is an adaptor protein for E3 ubiquitin ligases that is frequently mutated in a wide range of cancers, including prostate, breast, endometrial, liver, and colon cancers." (PMID 39540935, 2024). "In particular, the increased RIPK3 level by SPOP depletion sensitized LPS/sMAC/zVAD-induced necroptosis in HT-29 colon cancer cells." (PMID 39540935, 2024). "Based on the levels of RIPK3 and SPOP endogenous expression in colon cancer cell lines, including HT-29, HCT115, DLD-1, HCT116, WiDr, and SW480, HT-29 cells were selected for further experiments because they exhibited detectable levels of RIPK3 and SPOP, making them suitable for the present study." (PMID 39540935, 2024). "Furthermore, increased cellular proliferation and migration observed in SPOP-depleted HCT116 colon cancer cells could be partially reversed by additional depletion of HDAC6, suggesting that HDAC6 is a key downstream effector of SPOP's tumor suppressor function." (PMID 40521202, 2025). "The deletion of SPOP, which led to increased stability of the RIPK3 protein, intensified LPS/sMAC/zVAD-induced necroptotic cell death in colon cancer cells." (PMID 39540935, 2024). "More importantly, increased cellular proliferation and migration in SPOP-depleted HCT116 colon cancer cells could be partly reversed by additional depletion of HDAC6, suggesting that HDAC6 is a key downstream effector for SPOP tumor suppressor function." (PMID 28599312, 2017).